CFTR (CF transmembrane conductance regulator)
Diseases named in the same sentence as CFTR in open-access papers (continued):
Sharing a sentence is not in itself a finding about the gene and the disease.
lactic acidosis (1 paper, 2012). Metabolic acidosis characterized by the accumulation of lactate in the body. "However, the effects of lactic acidosis on inflammation-induced transcription factors remain controversial, and the mechanism by which lactic acid induced enhancement of CFTR gene and protein expression requires further investigation." (PMID 23226244, 2012).
medullary thyroid cancer (1 paper, 2021). "Other potential indications for cinacalcet include medullary thyroid cancer–associated diarrhea, bile acid diarrhea, and tyrosine kinase inhibitor diarrhea, in which increased CFTR-mediated Cl– secretion is a major cause of diarrhea." (PMID 33400691, 2021).
metastasis (1 paper, 2016). The spread or migration of cancer cells from one part of the body (where they first appeared) to another. "Our results show that the reduced expression of CFTR is correlated with advanced disease stage and distant metastasis, but not tumor size or lymph node metastasis, indicating low CFTR expression is related to more advanced disease." (PMID 27769067, 2016).
metastatic cancer (1 paper, 2018). A carcinoma which has spread from the original site of growth to another anatomic site. "The close association of EMT (Particularly type-3 EMT which leads to metastasis) with cancer led to the identification that CFTR is often down-regulated in metastatic cancer cells." (PMID 30021582, 2018). "When a metastatic cancer cell line was made to over-express CFTR, upon subcutaneous injection into mice a reduced number of metastatic lung growths resulted compared to the same cell line without CFTR over-expression." (PMID 30021582, 2018).
mitochondrial DNA depletion syndrome (1 paper, 2022). The mitochondrial DNA (mtDNA) depletion syndrome (MDS) is a clinically heterogeneous group of mitochondrial disorders characterized by a reduction of the mtDNA copy number in affected tissues without mutations or rearrangements in the mtDNA. "Three of the detected genes, POLG, NPC1, and CFTR, were not included in the old 18-gene panel and patients harboring variants in them were molecular diagnosed with mitochondrial DNA depletion syndrome, NPC and CF, respectively." (PMID 37168916, 2022).
multiple endocrine neoplasia syndrome type 1 (1 paper, 2022). "Only 10% of PDACs are linked to genetic mutations such as BRCA2, STK11/LKB1, CFTR, and PRSS1 or to familial syndromes such as Von Hippen-Lindau disease (VHL), multiple endocrine neoplasia syndrome type 1 (MEN-1), and neurofibromatosis type 1 (NF-1)." (PMID 36611999, 2022).
myocardial disease (1 paper, 2020). "The influence of the Arg/NO pathway and CFTR deficiency on myocardial disease and cardiovascular risk could become a field of interest in future research on CF." (PMID 32604946, 2020).
neural tumors (1 paper, 2025). "Overall, by comparing to PA, we identified subtype-specific pathways in neural tumors: PAK signaling (PTPRD and PDGFRB) in GBM, regulation of CFTR activity pathway (PPP2R1A, RABEP1) in MBL, and ERK signaling (IRS4 and ATM) in NBL." (PMID 40768543, 2025).
neuroendocrine tumor (1 paper, 2021). "This could be due to silencing of the CFTR enhancer function during neuroendocrine tumor development, a hypothesis requiring further validation." (PMID 34274970, 2021).
ocular infection (1 paper, 2024). "To examine the antiviral effect of CFTR inhibitors in infected mice, we established an ocular infection model using the HSV-1 F strain and a vaginal infection model using the HSV-2 333 strain in WT BALB/c mice." (PMID 39205282, 2024).
osteosarcoma (1 paper, 2019). A usually aggressive malignant bone-forming mesenchymal neoplasm, predominantly affecting adolescents and young adults. "The CSE-MEM system, used U2OS cells, an osteosarcoma epithelial cell line, stably transfected with F508del CFTR tagged with a Pro-link moiety at the C-terminal and a plasma membrane located EA (enzyme acceptor) moiety." (PMID 31143125, 2019).
ovarian failure (1 paper, 2022). "Thus, the mechanisms of subfertility among CF females are not fully understood despite several identified contributing factors: hypothalamic factor, anovulation, ovarian failure, cervical and tubal causes, with the CFTR protein as a common denominator." (PMID 35265034, 2022). "Ovarian failure was also suspected as animal studies have shown that the CFTR protein was expressed in the hypothalamus and in the ovaries." (PMID 35265034, 2022).
pneumothorax (1 paper, 2025). Abnormal presence of air in the pleural cavity. "Of the two additional CF patients who underwent AE and started CFTR modulators, one (P09) remained free of recurrence during follow-up (27 months), while the other (P07) did not experience recurrent haemoptysis but died 4 years after the single AE procedure due to spontaneous pneumothorax." (PMID 41439858, 2025).
Polyuria (1 paper, 2010). An increased rate of urine production. "PPARγ agonists alter the density of CFTR expression in the plasma membrane but do not interfere with the action of vasopressin on water transport or cause polyuria as observed with vasopressin V2 receptor antagonists." (PMID 21052534, 2010).
RASopathy (1 paper, 2024). Developmental syndromes caused by germline mutations (or in rare cases by somatic mosaicism) in genes that alter the Ras subfamily and mitogen-activated protein kinases that control signal transduction. "Prenatal genetic testing of a RASopathy-related genes panel resulted in negative, as well as the study of the most frequent CFTR mutations in both parents." (PMID 38702428, 2024).
respiratory system cancer (1 paper, 2025). "Interestingly, people with PV CFTR demonstrated a lower prevalence of respiratory system cancer patients with CFTR PV (7% vs. 9% in those without PV CFTR variants)." (PMID 41147257, 2025).
schizencephaly (1 paper, 2025). "We report novel aspects such as the early-onset schizencephaly, the CFTR carrier status with borderline sweat chloride test, and the presence of multiple allergic and behavioral comorbidities, which underscores the importance of early genetic evaluation." (PMID 40843057, 2025).
scoliosis (1 paper, 2015). A congenital or acquired spinal deformity characterized by lateral curvature of the spine. "The majority of patients were nonsmokers women, scoliosis was present in 31% of patients, and CFTR mutation without CF diagnosis was found in 42% of affected individuals." (PMID 26106603, 2015).
sterility (1 paper, 2017). "Therefore, we evaluated whether CFTR expression in Slc9a3-/- mice was reduced and contributed to the sterility." (PMID 28384194, 2017).
thoracic cancer (1 paper, 2025). A primary or metastatic malignant neoplasm affecting the tissues of the thorax. "Our data are consistent with this as 9% of our APG cohort had a respiratory or thoracic cancer diagnosis and this cancer type only represented 7% of the cancers in the CFTR PV cohort." (PMID 41147257, 2025).
trichomoniasis (1 paper, 2021). An infection that is caused by Trichomonas. "Our results provide valuable insights into a better understanding of the pathogenesis of trichomoniasis and offer a novel therapeutic strategy for T. vaginalis infection via restoration of epithelial CFTR function." (PMID 33861752, 2021).
trisomy 21 (1 paper, 2025). A chromosomal disorder consisting of the presence of an extra chromosome 21. "It highlights the importance of considering CFTR‐related disorders in trisomy 21 patients with severe respiratory issues." (PMID 40241998, 2025).
Ureteral obstruction (1 paper, 2017). Obstruction of the flow of urine through the ureter. "Here, we report that CFTR expression is downregulated in the UUO (unilateral ureteral obstruction)-induced kidney fibrosis mouse model and human fibrotic kidneys." (PMID 28701694, 2017). "To test this hypothesis, we first examined whether CFTR expression was altered during the development of renal interstitial fibrosis by using unilateral ureteral obstruction (UUO) mouse model." (PMID 28701694, 2017).
uterine infection (1 paper, 2012). "However, a previous study conducted in mice suggested that LPS produced by uterine infection with C. trachomatis induced upregulation of CFTR and abnormal fluid accumulation in the mouse uterus at diestrus." (PMID 23061681, 2012).
xerostomia (1 paper, 2022). Dryness of the mouth resulting from reduced salivary secretion. "It is interesting to note that patients with xerostomia reported lower CFTR gene expression than those without xerostomia." (PMID 36476557, 2022).
Young syndrome (1 paper, 2025). Young syndrome is characterized by the association of obstructive azoospermia with recurrent sinobronchial infections. "Proper evaluation of an azoospermic male with sinopulmonary disease should therefore include CFTR mutation analysis to distinguish CF from conditions like Young syndrome." (PMID 41009940, 2025). "In contrast to CF, which is caused by CFTR gene mutations, the etiology of Young syndrome is unclear (possibly related to prior environmental exposures) and CFTR genetic testing is negative." (PMID 41009940, 2025).
Zinc deficiency (1 paper, 2022). A deficiency of the essential metal Zinc; an essential cofactor for many enzymes. "Compared with the Zn + ETEC group, the dZn+ETEC group showed lower relative expression of NHE3, but higher (p < 0.05) CFTR in the jejunum, implying that marginal zinc deficiency aggravated intestinal anion secretion and inhibited Na+ absorption in mice with ETEC challenge." (PMID 36136723, 2022).
genetic disease (537 papers, 2004 to 2026). "CF is a life-threatening genetic disorder caused by mutations in the CF transmembrane conductance regulator (CFTR) gene, leading to impaired respiratory function and recurrent severe respiratory symptoms." (PMID 40733537, 2025). "It is an autosomal recessive genetic disorder caused by mutations in (CFTR)-encoding gene, the cystic fibrosis transmembrane conductance regulator (CFTR) gene." (PMID 39134095, 2025). "CF is a severe genetic disorder caused by mutations in the CFTR gene, leading to an imbalanced liquid homeostasis in lung epithelia cells." (PMID 41416220, 2025). "Overall, 12% of patients had genetic disorders: microdeletions of the azoospermia factor (AZF) in the Yq region (50% of patients with genetic disorders), Klinefelter's syndrome (24%), CFTR gene mutations (11%), and other genetic disorders (15%)." (PMID 40047164, 2025). "CF is a life-limiting genetic disease caused by mutations in the CF transmembrane conductance regulator (CFTR) gene and affects over 100,000 individuals worldwide." (PMID 41115837, 2025). "CF is a genetic disorder characterized by mutations in the gene encoding the CF Transmembrane conductance Regulator (CFTR), which controls the passage of chloride ions through the membrane of epithelial cells, including the airway epithelium." (PMID 38673985, 2024). "CF is a multisystem genetic disease caused by mutations in the gene encoding the CF transmembrane conductance regulator (CFTR) protein." (PMID 39108933, 2024). "Treatment of CF with small molecules to increase cell-surface CFTR expression and thereby protein function is a first successful example of mutation-specific therapy for genetic diseases." (PMID 36778025, 2023). "This genetic disease is caused by mutations in the gene encoding cystic fibrosis transmembrane conductance regulator (CFTR)." (PMID 35303381, 2023). "It is an autosomal recessive genetic disease with mutations in the gene encoding the CF transmembrane conductance regulator (CFTR) protein." (PMID 37808186, 2023). "CF is a genetic disease caused by mutations in the CF transmembrane conductance regulator gene (CFTR), which is inherited in an autosomal recessive manner." (PMID 35742845, 2022). "Cystic fibrosis is a life-threatening genetic disorder, caused by mutations in the CF transmembrane-conductance regulator gene (cftr) that encodes CFTR, a cAMP-activated chloride and bicarbonate channel." (PMID 36289287, 2022). "Studies of CFTR variants involved in CF play an important role in the research, diagnosis, surveillance and therapeutic development for this genetic disorder." (PMID 34740355, 2021). "This genetic disease is caused by variants of the gene encoding for the cystic fibrosis transmembrane conductance regulator (CFTR)." (PMID 33407736, 2021). "In conclusion, we identified candidate base editor RNPs for CFTR mutation repair and demonstrate a broadly applicable gene correction strategy for CF and other genetic diseases." (PMID 34520545, 2021). "Cystic fibrosis is a genetic disease due to CF transmembrane conductance regulator (cftr) gene mutations (mostly p.F508del mutation)." (PMID 33767218, 2021). "CF is a genetic disease caused by mutations in the CF transmembrane conductance regulator (CFTR) that results in an altered accumulation of airway metabolites and ions, especially succinate, itaconate, chloride and bicarbonate." (PMID 33302964, 2020). "This is a genetic disorder caused by mutations in the cystic fibrosis transmembrane conductance regulator (CFTR) gene." (PMID 31973051, 2020). "Cystic fibrosis transmembrane conductance regulator (CFTR) is a cAMP‐activated chloride channel, mutations of which lead to the most common lethal genetic disease." (PMID 32463592, 2020).
genetic disease (continued). "CF, being the most common lethal genetic disorder in Caucasians, is caused by mutations in the CFTR gene encoding for a cAMP-dependent chloride and bicarbonate channel mainly expressed in the apical membrane of secretory epithelial cells." (PMID 32962254, 2020). "It is an autosomal recessive genetic disease caused by mutations in the cystic fibrosis transmembrane conductance regulator (CFTR) gene." (PMID 29799381, 2018). "The disease is caused by a genetic disorder where a mutation exists in the CF transmembrane conductance regulator (CFTR) gene." (PMID 26955357, 2016). "Mutations in the cystic fibrosis transmembrane conductance regulator (CFTR) gene (OMIM 602421) are responsible for one of the best known autosomal genetic disorders contributing to reproductive failure." (PMID 25386751, 2014). "Utilizing the hits identified in high throughput screens for correctors of F508del-CFTR can accelerate the development of correctors for the protein trafficking defect underlying other genetic diseases." (PMID 23316740, 2013). "Paradoxically, the fact that the CFTR gene and its variants are among the most-studied and most-reported genetic diseases, with large dedicated national and international databases, can sometimes be a disadvantage rather than an advantage in terms of variant interpretation." (PMID 39062716, 2024). "CF is a genetic disease caused by the mutation of a gene that encodes a chloride channel located in the membrane of epithelial cells, the CF transmembrane conductance regulator (CFTR) protein." (PMID 38255969, 2024). "CF is a genetic disease caused by various CFTR gene mutations that lead to the dysfunction of CFTR." (PMID 36678791, 2023). "This is an autosomal recessive genetic disease caused by mutations in the gene encoding the cystic fibrosis transmembrane conductance regulator (CFTR) protein, a cyclic AMP activated chloride ion channel expressed in the apical membranes of epithelial cells in the lung and other organs." (PMID 24970162, 2013). "It is a lethal genetic disease primarily affecting the Caucasian population, caused by mutations in the CFTR (cystic fibrosis transmembrane conductance regulator) gene." (PMID 40332143, 2025). "Among well-characterized genetic diseases, AM included CF pathogenicity predictions for every possible CFTR single amino acid substitution." (PMID 38271453, 2024). "Taken together, our work provides important new insights that extend beyond the molecular pathology of CF and CFTR LOF to the global quest for the identification of molecular targets for genetic disorders using transcriptomics and proteomics approaches." (PMID 36759923, 2023). "The aim is to transform CF from a fatal disease to a treatable chronic disease through highly efficacious CFTR-directed medicines and specialized multidisciplinary care, as a model for other chronic disorders and genetic diseases." (PMID 36771186, 2023). "ddPCR is widely used for noninvasive prenatal detection of various types of mutations in many genetic diseases such as monogenic hereditary diabetes mellitus and mutations in the NF1 and CFTR genes." (PMID 33925253, 2021). "Since CF is a recessive genetic disorder, addition of a single copy of the properly functioning CFTR gene into affected CF airway cells is recognized as the only rational and feasible way to prevent or treat CF airway disease." (PMID 30538635, 2018). "Owing to the severity of this genetic disease, and to its frequency of occurrence, the CFTR gene has been the subject of an intense research focus for years." (PMID 22879944, 2012). "CF is a genetic disease, and the mutant protein is a chloride ion channel (CFTR) that normally regulates ion and fluid transport on the airway surface." (PMID 19621064, 2009). "We speculate that the method described here can also be used to target different regions of the CFTR gene, modifier genes, or other genes in order to model other genetic diseases." (PMID 37373413, 2023).
genetic disease (continued). "The acknowledgment of having a child with potential genetic disorders or malformations is not only experienced by the CFTR-carrier women, who represented the main focus of the study, but also by those who acknowledge that their pregnancy is at risk and require invasive diagnostic procedures." (PMID 35886548, 2022). "The disease is a genetic disorder with malfunctioning CFTR protein." (PMID 34832033, 2021). "CF is a genetic disorder potentially affecting all cells expressing CFTR." (PMID 28282951, 2017). "Unlike many genetic disorders, CFTR variants do not conform to an “all or none” disease paradigm." (PMID 40169970, 2025). "Lastly, since CF is a recessive genetic disorder, the addition of a single copy of the properly functioning CFTR gene into affected CF airway cells could represent the only rational and feasible way to prevent or treat CF airway disease for all CFTR mutation classes." (PMID 31698802, 2019). "If CFTR were to affect essential antimicrobial functions of PMNs in vivo, the involvement of several other organs would be expected, as is seen in PMN-specific genetic disorders, such as CGD." (PMID 28282951, 2017).